CYP2C19 (cytochrome P450 family 2 subfamily C member 19)
Diseases named in the same sentence as CYP2C19 in open-access papers (continued):
Sharing a sentence is not in itself a finding about the gene and the disease.
Stroke (continued). "Some studies suggested that for carriers of CYP2C19 LoFA with ESRS ≥3, clopidogrel combined with aspirin for TIA or acute cerebral infarction could still significantly reduce 90-day stroke recurrence and the incidence of combined vascular events compared with aspirin alone." (PMID 33685396, 2021). "The CYP2C19 genotype-guided strategy could reduce the occurrence of composite of stroke and myocardial infarction compared to a non-genotype-guided strategy for non-cardiogenic stroke patients aged 75 years or older who received clopidogrel." (PMID 33685396, 2021). "Our previous studies have demonstrated that carriers of CYP2C19 loss-of-function (LOF) alleles are associated with clopidogrel resistance, greater risk of stroke and composite vascular events than noncarriers among patients with IS or transient ischemic attack (TIA) treated with clopidogrel." (PMID 29707143, 2018). "However, our previous studies and the CHANCE trial had a short follow-up period, the relationship between stroke recurrence after IS and CYP2C19 genotype status is not well defined." (PMID 29707143, 2018). "However, there were no randomized-controlled trials according to CYP2C19 genotypes to investigate efficacy of clopidogrel and aspirin for the secondary prevention of stroke." (PMID 29707143, 2018). "Thus, given the recent publication of additional studies, in the present study we conducted an up-to-date meta-analysis to obtain a more precise estimation of the association between CYP2C19 LOF allele status and the clinical response to clopidogrel in non-East Asian patients with stroke or TIA." (PMID 38038819, 2024).
depression (54 papers, 2011 to 2026). "Current evidence from large genome-wide association studies (GWAS) does not support a causal or enrichment association between CYP2D6 or CYP2C19 variants and psychiatric disorders such as major depressive disorder (MDD) or anxiety disorders." (PMID 41378208, 2025). "Another study showed that the CYP2C19 genotype was associated with Sertraline titration in youth aged <19 years with a diagnosis of anxiety or depression." (PMID 41009999, 2025). "A clinical study was conducted to explore the association of CYP2C19 actionable variants translated into phenotypes with suicidal behavior in patients with depression who were using citalopram." (PMID 38420192, 2024). "The cytochrome P450 (CYP) 2C19 enzyme metabolize several antidepressants, and polymorphisms in the corresponding gene CYP2C19 influence plasma concentration and hence treatment outcomes in major depressive disorder." (PMID 36333412, 2023). "Previous research suggested that the CYP2C19 polymorphism is related to personality in female individuals, to depression traits in young males, and associated with basal ganglia and hippocampal volume in female individuals." (PMID 35931695, 2022). "The serotonin receptor 1A (HTR1A) rs878567 and CYP2C19 rs12248560 gene variants are associated with depression severity." (PMID 33920985, 2021). "Comparatively, a study carried out in 196 patients who were part of the GENDEP (Genome-Based Therapeutic Drugs for Depression) study found a significant association between CYP2C19 and CYP2D6 genotype and steady state escitalopram concentrations." (PMID 31616328, 2019). "The association of CYP2C19 metabolism status and side effects including hyperactivity, weight gain, gastrointestinal symptoms and insomnia was also investigated in pediatric patients prescribed escitalopram for anxiety or depressive disorders." (PMID 38420192, 2024). "We hypothesized that CYP2C19 polymorphisms are associated with major depressive disorder (MDD) remission in patients treated with ESC in the long term." (PMID 32509985, 2020). "In light of this information gap, we retrospectively analyzed electronic medical record (EMR) data to investigate the association between CYP2C19 metabolizer status and treatment outcomes following inpatient psychiatric hospitalization in youth with anxiety and/or depressive disorders." (PMID 30837874, 2019). "A total 202 patients with depression carrying the CYP2C19 gene were selected after the application of exclusion criteria." (PMID 41755565, 2026). "This study highlights the importance of CYP2C19 metaboliser status in treatment outcomes in young people given Escitalopram or Citalopram for the treatment of anxiety and/or depressive disorder." (PMID 41009999, 2025). "A clinical trial of 100 depression patients from Taipei found CYP2C19 poor metabolizers had higher serum levels of antidepressants." (PMID 39025838, 2024). "Genetic variations of CYP2C19 significantly impact the efficacy and safety of antidepressant medications, thus clinically influencing depression management." (PMID 38420192, 2024). "Moreover, the SM group had a significantly higher baseline score on the 21-item revised Beck Depression Inventory (BDI-IA) scale compared to the FM group, reinforcing the association between the CYP2C19 gene and MDD patients’ clinical characteristics." (PMID 39598373, 2024). "Several studies also explored CYP2C19 genotypes in the context of changes in the Hamilton Depression Rating (HAMD) Scale as a measure of therapeutic efficacy." (PMID 37765085, 2023). "Aim—The aim of this study was to evaluate differences in the Escitalopram and Citalopram efficacy and tolerability between different CYP2C19 genotype-based metabolizing categories in outpatients suffering from major depressive disorder (MDD)." (PMID 38137466, 2023). "This study shows that specific side effects such as nausea and depression are more prevalent in patients with an IM or PM phenoconverted phenotype of CYP2C19 and CYP2D6." (PMID 37693320, 2023).
depression (continued). "Recent studies have also demonstrated a correlation between low CYP2C19 activity and the severity of depression symptoms." (PMID 37239455, 2023). "Recent studies have suggested that impaired CYP2C19 metabolizers had higher self-rated Beck Depression Inventory-II scores than normal metabolizers." (PMID 36698099, 2023). "The CYP2C19 metabolizer status helped to explain and predict the likelihood of experiencing side effects in Israeli patients with depressive disorders who were prescribed Es/Citalopram." (PMID 38137466, 2023). "The activity of CYP2C19 in depression group increased approximately 3-fold from 0.025 ± 0.004 to 0.072 ± 0.005 ng/(min mg protein) (∗∗∗p < 0.001)." (PMID 36213502, 2022). "An association between CYP2D6 and CYP2C19 phenotypes and adverse effects secondary to TCA intake has been repeatedly described for patients treated for depression." (PMID 35745763, 2022). "CPIC recommends a dosing according to CYP2D6 and CYP2C19 phenotypes based on data collected thus far in patients with depression." (PMID 35745763, 2022). "There is an increasing body of clinical evidence linking pharmacogenetic (PGx) variability of CYP2D6 and CYP2C19 to drug blood concentrations, the treatment response, and the remission rates in patients with depression." (PMID 35890168, 2022). "We have studied the association between CYP2C19 and CYP2D6 gene variants and the treatment outcomes in children and adolescents, young adults, and adults with depression who were using (es)citalopram, sertraline, or fluoxetine." (PMID 35890168, 2022). "Distribution of CYP2D6 and CYP2C19 activity across the study sample of 50 depressive disorder patients, stratified by OCT1 genotype." (PMID 34093211, 2021). "Escitalopram (ESC) is one of the most commonly prescribed selective serotonin reuptake inhibitors (SSRIs) used for the treatment of both depression and anxiety disorders, and is mainly metabolized by CYP2C19." (PMID 32509985, 2020). "The apparent impact of CYP2C19 genotype in treatment response to citalopram and escitalopram in depression, together with the observations of differences in CYP2C19 pharmacogenetics of bipolar depressed patients, warrants further exploration." (PMID 32632502, 2020). "One such example involved a patient who was referred to clinic for uncontrolled depression while taking a CYP2C19-guided SSRI; upon medication reconciliation, the pharmacist learned that the patient was taking a CYP2D6-guided opioid as well." (PMID 32708920, 2020). "The genotype-guided recommendations of CYP2D6, CYP2C19, and SLC6A4 were associated with significantly higher measures of anxiety and depression in comparison to treatment as usual." (PMID 30837869, 2019). "In summary, CYP2C19 metabolizer status helped to explain the wide variability in treatment outcomes we observed in children and adolescents with anxiety and/or depressive disorders prescribed es/citalopram." (PMID 30837874, 2019). "Further research is warranted to develop personalized dosing recommendations based on CYP2C19 metabolizer status and assess their impact on treatment outcomes in pediatric patients with anxiety and/or depressive disorders." (PMID 30837874, 2019). "This is the first study to examine CYP2C19 metabolizer status and es/citalopram treatment outcome in children and adolescents with anxiety and depressive disorders." (PMID 30837874, 2019). "We report a retrospective study of electronic medical record data from 263 youth < 19 years of age with anxiety and/or depressive disorders prescribed escitalopram or citalopram who underwent routine clinical CYP2C19 genotyping." (PMID 30837874, 2019). "Taken together, the results highlight the potential of personalized dosing recommendations based on CYP2C19 metabolizer status to enhance treatment outcomes in youth with anxiety and/or depressive disorders." (PMID 30837874, 2019).
depression (continued). "Generally, in clinical practice, the first choice of drug for the treatment of depressive disorders during menopause is citalopram, because its metabolism is mainly through the cytochrome p450 isoenzyme CYP2C19." (PMID 29257042, 2017). "Another member of the CYP2C subfamily, CYP2C19, metabolizes drugs used in the treatment of malaria, HIV/AIDS, depression and thromboembolic diseases and genetic variants have been implicated in ADRs and treatment failure." (PMID 22563365, 2011). "Current guidelines for the use of genetic tests in major depression issued by the Clinical Pharmacogenomics Implementation Consortium (CPIC) are based on CYP2D6 and CYP2C19 polymorphisms which constitute the strongest evidence for pharmacogenomic guided treatment." (PMID 37490261, 2023). "Data on the impact of CYP2C19 genotype on antidepressant treatment effects in bipolar depression is scarce, but one study suggested that the CYP2C19 poor metabolism phenotype is more prevalent in treatment resistant bipolar disorder compared with treatment resistant major depressive disorder." (PMID 36333412, 2023). "Likewise, elevated CYP2C19 expression was related to depression, reduced hippocampal volume and the impairment of hippocampal serotonin homeostasis." (PMID 36257936, 2022). "However, CYP2C19 PMs had significantly increased rates of remission as well as marked improvement in symptoms of depression when compared with normal metabolizers." (PMID 31850065, 2019). "Specifically, the absence of CYP2C19 is associated with a lower prevalence of depression." (PMID 40362522, 2025). "The present study aims to assess the association between CYP2C19 SSRI inferred metaboliser status based on individual CYP2C19 polymorphisms and patient-reported efficacy of sertraline, citalopram and escitalopram in the Australian Genetics of Depression Study (AGDS)." (PMID 35094016, 2022). "In contrast, Fabbri and colleagues found in a meta-analysis that CYP2C19 poor-metabolizers had higher side-effects compared to extensive metabolizers at weeks 2–4, however, also showed higher symptom improvement and remission in major depression when treated with citalopram or escitalopram." (PMID 32632502, 2020). "SSRIs are first-line agents for the treatment of depression and anxiety and have a CPIC guideline based off their interaction with CYP2C19 and CYP2D6." (PMID 37645439, 2023). "Majority of the medications used for treatment of depression are metabolized by CYP450 enzymes, specifically, CYP2D6 and CYP2C19." (PMID 35496293, 2022). "The CYP2C19 and CYP2C9 activities of liver microsomes in the depression group were significantly increased than those in the control group." (PMID 36213502, 2022). "The CYP2C19 and CYP2C9 activity of liver microsomes in the CUMS-induced depression group were significantly higher than that in the control group (∗∗p < 0.01)." (PMID 36213502, 2022). "Within the Phase 1 enzyme P450 family two isoforms, CYP2C19 and CYP2D6 are the main pathways by which two thirds of all psychiatric medications to treat depression are metabolised." (PMID 32796505, 2020). "Reimbursement data by testing indications (e.g., ICD-10 codes for depression, anxiety, GERD) is needed to educate patients on which insurance providers are generally reimbursing for CYP2C19, CYP2D6, and/or panel testing." (PMID 32708920, 2020). "In adults being treated for depression, dose reduction or alternate therapy is recommended by CPIC if the patient is known to be a CYP2C19 or CYP2D6 poor metabolizer." (PMID 29099060, 2017). "Since, in the current study, depression is the disease state related to the greatest number of PGx gene–drug pairs having both FDA/CPIC categorizations, it is worth highlighting that CYP2C19 and CYP2D6 are primarily responsible for the metabolism of those antidepressant medications." (PMID 38535119, 2024).
depression (continued). "However, further detailed studies are required to confirm the role of CYP2C19 in 5-HT1A biochemical signaling, and consequently, hippocampal volume and depression." (PMID 36362270, 2022). "Improvement in depression HDRS scores were observed in CYP2C19-NM (p < 0.001) and IM (p < 0.02), with no response in CYP2C19-PM and minimum improvement in CYP2C19-UM." (PMID 33920985, 2021). "AmpliChip CYP450 and some TaqMan single nucleotide variant (SNV) and copy number variant (CNV) data in the Genome-based therapeutic drugs for depression (GENDEP) study were used to select 95 samples (out of 853) to represent as broad a range of CYP2D6 and CYP2C19 genotypes as possible." (PMID 34811360, 2021). "In particular, the absence of CYP2C19 is correlated with a lower prevalence of depression." (PMID 36362270, 2022). "In a large Danish population-based case cohort study of patients with mental disorders, including depression (n = 51,464), it was found that 73% of the cases exhibited CYP2D6 and CYP2C19 non-NM phenotypes." (PMID 39444600, 2024). "An additional possibility is that in the Middle East the frequency of non-normal metaboliser phenotypes of CYP2C19 and CYP2D6 might be inferior to other ethnic groups around the world, reducing the overall spectrum of actionable genotypes for pharmacogenomic guided treatment in major depression." (PMID 37490261, 2023).
breast carcinoma (44 papers, 2008 to 2025). "A meta-analysis has confirmed the association between the CYP2C19*2 and *17 genotypes with improved survival rates in breast cancer patients treated with tamoxifen." (PMID 41295207, 2025). "Further research involving 230 breast cancer patients identified significant associations between CYP2C19 and CYP2B6 genotypes and OS." (PMID 39598531, 2024). "Genetic variants (CYP2D6 and CYP2C19 genotypes), tamoxifen and metabolites concentrations, baseline characteristics, and breast cancer recurrence from the CYPTAM study (NTR1509) were used." (PMID 33432065, 2021). "Another investigation reported frequencies of CYP2C19*2 polymorphism in breast cancer patients on triple therapy, including cyclophosphamide, fluorouracil, and doxorubicin." (PMID 34308762, 2021). "Several studies indicate that CYP2C19 variants are associated with differences in baseline breast cancer risk, likely due to the inherent role of CYP2C19 in the metabolism of estrogen." (PMID 28798474, 2017). "Because of an established role in estrogen metabolism, CYP2C19 variants have been tested for association with breast cancer risk." (PMID 28391240, 2017). "Another CYP2C19 allele, CYP2C19*17, defining an ultra-rapid metabolizer phenotype, has previously been associated with a decreased risk for breast cancer." (PMID 25466287, 2014). "Our results indicate that an inherited defect in the CYP2C19 gene with a role in estrogen catabolism has an influence on the molecular subtype of breast cancer and is significantly associated with triple-negative tumors." (PMID 25466287, 2014). "One CYP2C19 allele, CYP2C19*17, defining an ultra-rapid metabolizer phenotype, has previously been associated with a decreased risk for breast cancer." (PMID 22737080, 2012). "We studied the association of the functionally significant variant alleles of CYP3A4, CYP3A5, CYP2B6, CYP2C8, CYP2C9 and CYP2C19 with the clinical response to neoadjuvant chemotherapy in breast cancer patients." (PMID 22702493, 2012). "Here, we studied the association of functionally significant variant alleles of CYP3A4, CYP3A5, CYP2B6, CYP2C8, CYP2C9 and CYP2C19 with the clinical response to neoadjuvant chemotherapy in breast cancer patients." (PMID 22702493, 2012). "Curiously, based on their function both ESR2 and CYP2C19 have long been considered strong candidate genes for breast cancer susceptibility." (PMID 22737080, 2012). "Additionally, the CYP2C19*17 variant has been linked to a reduced risk of breast cancer, as it also metabolizes endogenous estrogen, potentially lowering its levels and impacting cancer progression." (PMID 41295207, 2025). "We hypothesised that the polymorphisms of the CYP2D6 and CYP2C19 genes can affect the efficiency of tamoxifen in the treatment of patients with breast cancer." (PMID 38681733, 2024). "However, some studies suggest that the activity of CYP2C19 in breast cancer patients with CYP2C19*17(C-806T) allele was enhanced, and the application of TAM treatment was beneficial to those patients." (PMID 34868931, 2021). "Consistently with the notion that estrogen exposure is lower in carriers of the high-activity CYP2C19*17 allele, ultrarapid metabolizers have been shown to present lower incidence of breast cancer, and lower recurrences of hormonal sensitive breast cancer after treatment with tamoxifen." (PMID 34497262, 2021). "CYP2C19*3 was identified to be associated with breast cancer risk in women." (PMID 33192522, 2020). "In contrast, a decreased breast cancer risk for carriers of the CYP2C19*17 allele was observed in German women, and a meta-analysis has found that CYP2C19*2 and CYP2C19*17 genotypes are associated with increased survival of breast cancer patients treated with tamoxifen." (PMID 33192522, 2020).